FABP4 (fatty acid binding protein 4)
Diseases named in the same sentence as FABP4 in open-access papers (continued):
Sharing a sentence is not in itself a finding about the gene and the disease.
Hepatic steatosis (continued). "Therefore, the aim of this work was to analyze the relationship between circulating FABP4 and liver steatosis assessed by FLI in patients at increased cardiometabolic risk." (PMID 34966292, 2021). "Next, we explored the role of serum FABP4 as independent indicator of liver steatosis." (PMID 34966292, 2021). "Serum FABP4 levels were higher in individuals with liver steatosis." (PMID 34966292, 2021). "The results of protein expression including upregulation of SIRT1 and PGC1 and downregulation of FAS and FABP4 in liver tissue of the NDS group provided evidences to support amelioration of hepatic steatosis of APS1 might through the gut-liver axis." (PMID 29670255, 2018). "Treatment with recombinant bone morphogenetic protein 9 (BMP9) alleviated hepatic steatosis and decreased liver macrophage infiltration in mice fed with a high fat diet, partially via decreasing the FABP4 promoter chromatin accessibility and the subsequent reduction in the FABP4 expression." (PMID 35052876, 2022). "Therefore, although further studies are necessary to fully explore this hypothesis, serum FABP4 may not only reflect liver steatosis, but also NASH." (PMID 34966292, 2021). "Therefore, we speculated that BMP9 might alleviate hepatic steatosis and improve glucose metabolism by downregulating Cers6, Cidea and Fabp4 expression." (PMID 33603666, 2020). "Therefore, FABP4 may not only reflect liver steatosis, but also advanced stages of MAFLD." (PMID 35052876, 2022). "The aim of this study was to assess the relationship between FABP4 and the fatty liver index (FLI) in metabolic patients and to evaluate its potential role in the fatty liver disease." (PMID 34966292, 2021). "In humans and rats, fatty liver disease is promoted by sterol regulatory element–binding protein 1 (SREBP1) and fatty acid-binding protein 4 (FABP4)." (PMID 34206460, 2021). "Chlorogenic acid was reported to curb hepatic steatosis, which correlated to suppression on hepatic gene expression of peroxisome proliferator-activated receptor γ, CD36, and fatty acid binding protein 4 induced by HFD." (PMID 30618733, 2018). "Among the synthetic FABP4 inhibitors developed to date, BMS309403, which competitively inhibits the binding of endogenous fatty acids, protects against several metabolic disturbances, including fatty liver disease." (PMID 35052876, 2022). "Rather, hepatic steatosis occurs through increased NEFA flow from the diet or adipose tissue and heightened uptake by the liver, facilitated by the elevated levels of fatty acid transporters CD36 and FABP4, as shown here." (PMID 33746771, 2021). "In contrast to what has been reported in human and mouse studies, the highly significant upregulation of PPARG, CD36, LPL, and FABP4 in the liver of the minipigs do not result in development of abundant hepatic steatosis." (PMID 32205840, 2020). "However, GSPE treatment remarkably reduced lipid accumulation and CD36 and FABP4 expression in the liver of PFOS-exposed mice, suggesting that GSPE can reverse hepatic steatosis through modulating lipid metabolism." (PMID 33457418, 2020). "Fenugreek decreased hepatic expression of fatty acid-binding protein 4 and increased subcutaneous inguinal adipose tissue expression of adiponectin, but did not prevent hepatic steatosis." (PMID 28986580, 2017). "In our study, after the NLX treatment, we did not observe changes in hepatic steatosis in the histological examination; however, at the molecular level, we observed a significant decrease in Fabp4 mRNA expression in the livers of the ApoE−/− mice (fold change 0.8)." (PMID 40868056, 2025). "PPAR-γ is known as an “energy balance receptor” and is a crucial regulator of many PPRE-containing genes such as FABP4 and CPT1A having an essential function in fat metabolism and lipogenesis, resulting in the decline of the circulating blood lipids and inhibition of the liver steatosis." (PMID 34306045, 2021).
Hepatic steatosis (continued). "The molecular mechanism involving APS1-ameliorated hepatic steatosis including sirtuin (SIRT) 1, peroxisome proliferator-activated receptor gamma coactivator 1 (PGC1), lipid synthesis factors (ACC, FAS) and fatty acid transporter FABP4 was investigated by immunoblot assay." (PMID 29670255, 2018). "In addition, in the hepatic steatosis model, only E6446, not the four candidate compounds, suppressed the accumulation of TG content, the formation of lipid droplets and the expression of C/ebpα, Fasn, and Fabp4." (PMID 37777801, 2023). "Fatty acid binding protein 4 (FABP4) has been proposed as potential biomarker for the ectopic fat accumulation in non-adipose tissues, although its role reflecting liver steatosis in metabolic patients is not fully explored." (PMID 34966292, 2021). "Our results show that Göttingen Minipigs do not develop abundant hepatic steatosis in spite of the significantly increased expression of PPARG, FABP4, CD36, and LPL in the liver." (PMID 32205840, 2020). "Although Fabp4−/− mice were not protected against fatty liver disease, inhibition of FABP4 suppressed fatty liver infiltration, similar to the liver phenotype of Fabp4−/−Fabp5−/− mice." (PMID 22121495, 2011).
Hypertension (50 papers, 2011 to 2025). The presence of chronic increased pressure in the systemic arterial system. "Elevated levels of circulating FABP4 are biomarkers associated with inflammation, hypertension, and cardiovascular incidents." (PMID 38598492, 2024). "Higher cord plasma FABP4 levels were associated with family history of hypertension, cesarean section delivery and higher birth weight z scores." (PMID 34621244, 2021). "After multivariable adjustment, only hypertension was independently associated with FABP4 concentrations." (PMID 33287461, 2020). "Elevated circulating FABP4 levels have been associated with a family history of hypertension." (PMID 34621244, 2021). "As an adipokine, FABP4 is also closely associated with hypertension." (PMID 26752184, 2016). "Our results showed that a unique cluster of fibroblasts (FABP4+ fibroblasts) appeared in the presence of lipid overload and hypertension-induced cardiac remodeling." (PMID 39198543, 2024). "Consistent with the findings in humans, the change in FABP4+ fibroblasts was most significant in the context of hypertension combined with hyperlipidemia in mice." (PMID 39198543, 2024). "Furthermore, we found that the expression of a new specific subgroup (Fabp4+ fibroblasts), which is associated with lipid metabolism and triglyceride metabolism, increased in patients with heart failure caused by the combination of coronary artery disease and hypertension." (PMID 39198543, 2024). "In the present study, we provided evidence that CD34+ cells can differentiate into a special type of fibroblast called FABP4+ fibroblasts in the presence of hyperlipidemia and hypertension." (PMID 39198543, 2024). "Together, these data suggest that hypertension combined with hyperlipidemia can further accelerate myocardial fibrosis compared to hyperlipidemia alone, especially in the FABP4+ fibroblast subcluster." (PMID 39198543, 2024). "Our results also revealed that diastolic blood pressure was an independent factor for FABP4, indicating the potential impact of FABP4 on hypertension." (PMID 26752184, 2016). "Second, FABP4 lead to increased blood pressure in patient with hypertension, as well as atherogenic metabolic phenotype, another study found that increased second trimester plasma FABP4 independently predicted gestational hypertension or preeclampsia in gestational diabetes mellitus patients." (PMID 30969942, 2019). "The role of FABP4 in the pathogenesis of hypertension might be that FABP4 induces the transformation of the insulin-mediated endothelial nitric oxide synthase (eNOS) pathway, thus reducing NO production and endothelial dysfunction." (PMID 26752184, 2016). "However, only hypertension can be an independent predictor for FABP4 levels." (PMID 33287461, 2020). "Subsequently, the independent association between FABP4, ANGPTL3 and ANGPTL4, and CAD was assessed in various subgroups according to sex (male or female) and hypertension (with or without)." (PMID 38425231, 2024). "The FABP4 expression level was an independent risk factor for CAD in patients with hypertension, but not in those without hypertension (OR per 1 SD [95% CI]: 3.735 [1.368, 10.203], p = .010 vs. 1.508 [0.752, 3.026], p = .247; p for interaction = .260)." (PMID 38425231, 2024). "We stained heart sections from healthy people and patients with heart failure (with a history of hypertension and hyperlipidemia) using immunofluorescence and found that CD34 costaining for DDR2, POSTN, and FABP4 was greater in the heart failure group than in the control group." (PMID 39198543, 2024). "The subgroup of patients with hypertension showed higher FABP4 levels compared with patients with no hypertension (18.6 ng/ml [IQR 13.3–26.5] vs. 16.8 ng/ml [IQR 11.4–22.6]; P < 0.001)." (PMID 32075656, 2020). "Furthermore, the enhanced FABP4 concentrations were positively correlated with age, WHR, history of hypertension, DM, and serum creatinine levels, but negatively correlated with physical activity and HDL-C." (PMID 33287461, 2020).
Hypertension (continued). "Furthermore, FABP4 levels in mononuclear cell (MNC) culture supernatants were positively correlated with age, waist–hip ratio (WHR), history of hypertension, DM, and serum creatinine levels, but negatively correlated with physical activity and high-density lipoprotein (HDL)-C." (PMID 33287461, 2020).
coronary artery disease (46 papers, 2010 to 2025). "The relationships with the lipid/metabolic profiles aside, the resting serum FABP4 level has been associated with cardiovascular risks and diseases (e.g., age, BP, and coronary artery disease)." (PMID 39725654, 2024). "Complementary to these findings, a recent genome-wide association study of more than 500,000 individuals worldwide identified FABP4 as a common risk factor for both T2D and coronary heart disease (CHD)." (PMID 30705117, 2019). "Chronic kidney failure is a major risk factor for coronary disease and people with impaired kidney function have been reported to have higher concentrations of FABP4." (PMID 24455402, 2013). "A recent study reported that FABP4 was directly associated with NT-proBNP in Asian coronary artery disease patients, and during the review process of this study, the same group showed similar results to ours in HF patients." (PMID 23642261, 2013). "Therefore it raises the possibility of using FABP4 plasma levels as a biomarker for diagnosing coronary artery disease risk in diabetic patients." (PMID 37794302, 2024). "Also, FABP4 concentration is associated with both the development and severity of cardiovascular diseases (CVDs) including hypertension, coronary artery disease, ischemic stroke, and fatal arrhythmia." (PMID 39725654, 2024). "Lipid metabolism related factors, such as angiopoietin‐like protein 3 (ANGPTL3), angiopoietin‐like 4 (ANGPTL4), fatty acid‐binding protein 4 (FABP4) are newly discovered factors that can affect coronary artery disease (CAD)." (PMID 38425231, 2024). "Regression analysis demonstrated a significant association between FABP4 levels and DM-PAD after adjusting for age, sex, prior history of coronary arterial disease and white blood cells count (OR, 2.77; 95% CI, 1.81–4.31; p-value = 0.001)." (PMID 32887447, 2020). "FABP4 had an AUC of 0.79, which improved to 0.86 after adjusting for age, sex and prior history of coronary arterial disease." (PMID 32887447, 2020). "Increased FABP4 level is an important cardiometabolic predictor, prognostic factor in end-stage renal disease or coronary artery disease (CAD)." (PMID 30993401, 2019). "The accumulation of cardiac fat is also associated with higher levels of pro-inflammatory cytokines such as IL-6, IL-1, TNF-α, and the expression of adipokine fatty acid-binding protein 4 (FABP4) that are associated with the development of MetS and the extent of coronary artery disease." (PMID 33752666, 2021). "FABP4 from epicardial fat might have adverse effects on coronary artery disease and atrial fibrillation." (PMID 32727561, 2020). "Different associations between men and women for FABP4 have already been described for coronary artery disease and carotid atherosclerosis: FABP4 was more closely related with coronary artery disease in women compared to men and FABP4 had a greater impact on coronary atherosclerosis in women." (PMID 32727561, 2020). "Serum FABP4 levels may be also related to carotid and coronary atherosclerosis, in addition to coronary artery disease (CAD)." (PMID 33287461, 2020). "However, in a different publication, FABP4 was described to be independently associated with coronary artery disease in men (but no women have been included in the investigation)." (PMID 32727561, 2020). "Recent studies also showed an independent correlation of elevated serum FABP4 with NT-proBNP in heart failure patients or deterioration of LV systolic function in non-obese patients hospitalized for acutely decompensated heart failure and in patients with coronary artery disease." (PMID 25142635, 2014). "Moreover, in recent studies, increased serum FABP4 levels were also shown to predict the occurrence of micro- and macro-vascular complications in T2D, such as diabetic retinopathy (DR), diabetic nephropathy (DN), coronary artery disease (CAD) and acute ischemic stroke (AIS)." (PMID 34174950, 2021).
coronary artery disease (continued). "The aim of this study was to investigate epicardial adipose tissue (EAT) omentin-1 and FABP4 gene expression in obese and non-obese patients with coronary artery disease (CAD)." (PMID 34609443, 2021). "Despite a lack of direct evidence of an association between FABP4 and SCD in humans, previous studies have reported associations between FABP4 and risk factors for SCD, including coronary artery disease." (PMID 24455402, 2013). "Therefore, we examined both myocardial and perivascular adipose tissue expression of ATGL, CGI-58, G0S2, HSL, and FABP4 at the transcript (mRNA) and protein levels in patients with multivessel coronary artery disease and compared them with control patients without coronary atherosclerosis." (PMID 31979197, 2020).
prostate carcinoma (39 papers, 2010 to 2025). A carcinoma that arises from epithelial cells of the prostate gland. "Thus, FABP4 and its associated signaling pathway could serve as promising targets for the chemoprevention and/or therapy of prostate cancer." (PMID 41226657, 2025). "FABP4 can exert endocrine and exocrine effects as it is secreted from adipocytes and macrophages, and its association with prostate cancer supports further assessment of the regulatory relationships between these cells and prostate cancer progression and metastasis." (PMID 39402324, 2024). "In particular, an increase in invasion was observed in prostate cancer cells exposed to fatty acid-binding protein 4 (FABP4)." (PMID 40002869, 2025). "In prostate cancer, exogenous FABP4 promotes tumour growth and metastasis by activating the PI3K/AKT and MAPK/ERK pathways." (PMID 38610991, 2024). "BMS309403, a biphenyl azole compound, effectively reversed the enhanced invasiveness induced by exogenous FABP4 in prostate cancer." (PMID 38610991, 2024). "The FABP4 blocker also suppressed the subcutaneous growth of prostate cancer cells and lung metastasis in an animal model." (PMID 36060264, 2022). "FABP4 was highly expressed in bone metastases of prostate cancer in both obese mouse models and clinical samples." (PMID 36060264, 2022). "Overexpression of FABP4 in prostate cancer results in the upregulation of MMP-2 and MMP-9, which promotes the invasion of cancer cells." (PMID 34685761, 2021). "A very low content of FABP4 was found in human prostate cancer cells as compared with normal prostate epithelial cells, suggesting a role as tumor suppressor for this chaperone." (PMID 32856199, 2020). "Another mouse xenograft experiment concluded that HFD enhanced prostate cancer metastasis and invasiveness through FABP4 and interleukin-8 upregulation." (PMID 31052319, 2019). "Similar up-regulation of FABP4 was observed in tumor cells cocultivated with BM-Ad and in murine models of bone metastasis of prostate cancer." (PMID 28915700, 2017). "In support of this concept, one previous study mentioned that BM adipocytes modulate the fatty acid binding protein 4 (FABP4)-interleukin-1 beta (IL-1β) pathway in prostate cancer cells, when homing into bone." (PMID 27049717, 2016). "A similar observation of adipocyte-induced increase in FABP4 expression has been reported in PC3 prostate cancer cells." (PMID 25866768, 2015). "The same study also reported an increased expression of FABP4 in prostate cancer bone metastasis from high-fat diet mice and prostate cancer patients." (PMID 25866768, 2015). "Further studies from Izumi and colleagues demonstrated that FABP4 treatment promoted serum-induced prostate cancer cell invasion in vitro and treatment with FABP4 inhibitor in mice reduced lung metastasis of prostate cancer cells." (PMID 25569080, 2015). "Immunohistochemical findings from experimental bone tumors were then confirmed in tissue samples from prostate cancer patients, which showed FABP4 is strongly localized to endothelial cells but it is also highly present in tumor cells." (PMID 24240026, 2013). "We show that FABP4 is highly overexpressed in prostate skeletal tumors from obese mice and in bone metastasis samples from prostate cancer patients." (PMID 24240026, 2013). "Moreover, in prostate cancer animal model the blockade of FABP4 diminished the tumour growth and metastasis, partly by inducing prostatic epithelial cell DNA damage and apoptosis." (PMID 39941741, 2025). "Elevated expression of FABP4 and secretion of FABP4 by prostate cancer cells trigger the invasiveness of the prostate cancer by stimulation of matrix metalloproteinases (MMPs) via phosphatidylinositol 3-kinase (PI3K) and mitogen-activated protein kinase (MAPK) signalling pathways." (PMID 39941741, 2025). "Additionally, FABP4 facilitates prostate cancer aggressiveness through increased secretion of IL-6 and IL-8." (PMID 39941741, 2025).